AKR1B1 (aldo-keto reductase family 1 member B)
Diseases named in the same sentence as AKR1B1 in open-access papers (continued):
Sharing a sentence is not in itself a finding about the gene and the disease.
cataract (23 papers, 2010 to 2025). Partial or complete opacity of the crystalline lens of one or both eyes that decreases visual acuity and eventually results in blindness. "Four genes, including ESR1, MAPK14, CASP3, and AKR1B1, were shared between CS compound targets and cataracts' targets, indicating their possible anticataract action." (PMID 35860180, 2022). "Network analysis suggested that four shared targets may play crucial roles in the treatment of cataracts, including aldose reductase (AKR1B1), caspase-3 (CASP3), mitogen-activated protein kinase 14 (MAPK14), and estrogen receptor (ESR1)." (PMID 35860180, 2022). "D3T downregulated AKR1B1-induced AMPK and caused an AcSOD2 imbalance, thereby decreasing EMT in the LECs, which is known to be a potentially important factor in the pathogenesis of cataracts in rats with fructose-induced DM." (PMID 34356319, 2021). "AKR1B1 inhibitors may be promising pharmacological agents that prevent cataracts in diabetic patients." (PMID 32218152, 2020). "In conclusion, we found that EMT in the DM cataract occurs through AKR1B1-enhanced AGE and ROS generation in LECs from DM (+) cataract patients." (PMID 32218152, 2020). "Consistently, we observed that increased AKR1B1 was significantly correlated with decreased LEC density, which enhanced EMT in DM (+) cataract patients." (PMID 32218152, 2020). "Immunofluorescent staining showed that AKR1B1 and RAGE were significantly higher in epithelial human lens of DM (+) compared to DM (−) cataracts." (PMID 32218152, 2020). "Although the gene expression of MAPK14 and AKR1B1 was not affected by CS treatment, the activities of these proteins required further validation to identify their roles in the treatment of cataracts by CS." (PMID 35860180, 2022). "In the present study of diabetic eye disease, we hypothesize that EMT in DM cataracts occurs through AKR1B1-enhanced AGE, and reactive oxygen species (ROS) generation influences the cataract development in DM." (PMID 32218152, 2020). "Here, we evaluated AKR1B1 and RAGE expressions in DM (+) and DM (−) cataract patients." (PMID 32218152, 2020).
neuropathy (23 papers, 2008 to 2025). A disorder affecting the nervous system that manifests with pain, tingling, numbness, and/or muscle weakness. "AKR1B1 or human aldose reductase mediates the first step in the reduction of glucose to sorbitol in the polyol pathway, which under hyperglycemic conditions is co-responsible for the diabetic complications (i.e., retinopathy, neuropathy, nephropathy, cataract)." (PMID 35328588, 2022). "Aldose reductase (EC 1.1.1.21; AKR1B1), the first enzyme in the polyol pathway, is likely implicated in a variety of pathological states such as nephropathies, retinopathies, neuropathies, cardiopathies, cataract, and cancer, mainly related to its action on glucose in hyperglycaemic conditions." (PMID 32640594, 2020).
type 2 diabetes (23 papers, 2008 to 2025). "Petra Haberzettl (University of Louisville, USA) reported on the interesting observation that aldose reductase (AKR1B1) protects against age-dependent insulin resistance in type 2 diabetes, which she concluded might be due to the fact that AKR1B1 metabolizes excess glucose via the polyol pathway." (PMID 23199258, 2012). "We investigated the association of nine functionally significant polymorphisms in this set of five oxidation pathways modulation genes (ADPRT1, AKR1B1, RAGE, GFPT2 AND PAI-1) with CRI among Asian Indians with type 2 diabetes." (PMID 20353610, 2010).
Nephropathy (21 papers, 2008 to 2025). A nonspecific term referring to disease or damage of the kidneys. "They concluded that the degree of AKR1B1 gene expression modulates the risk for nephropathy in type 1 DM." (PMID 28805547, 2017). "They found significant differences in AKR1B1/beta-actin mRNA ratios between both diabetics and non-diabetics with kidney disease and controls." (PMID 28805547, 2017).
Obesity (20 papers, 2014 to 2025). Accumulation of substantial excess body fat.
colon cancer (14 papers, 2014 to 2025). "Further, in patients with colon cancer, high expression of Akr1B1 is associated with enhanced motility and poor clinical outcome." (PMID 38283991, 2023). "With the help of these powerful aldo-keto reductase inhibitors, it may be possible to synthesize potential new pharmaceuticals that cure colon cancers associated with aberrant expression of the AKR1B1 or AKR1B10 protein." (PMID 36301939, 2022). "As we observed AKR1B1 expression in CAFs, we further aimed to evaluate this finding in a larger cohort of colon tumors (GSE39582)." (PMID 40396420, 2025). "To further substantiate our data, we carried out immunofluorescence staining with CD163 and AKR1B1 antibodies in FFPE tissues obtained from colon cancer patients." (PMID 40396420, 2025). "Our result showed that AKR1B1 was downregulated in colon tumor and in oxaliplatin-resistant cell lines." (PMID 35178443, 2022). "AR (AKR1B1) suppression has the potential to be a unique treatment strategy for the prevention of colon cancer metastasis." (PMID 35807227, 2022). "Our study purposes to discover the potent aldo-keto reductase inhibitors that may help to synthesize effective molecule with drug-likeness for the treatment of colon cancer specifically occur from the abnormal expression of either protein AKR1B1 or AKR1B10." (PMID 35807227, 2022). "The aberrant expression of aldo keto reductases (AKR1B1 & AKR1B10) has been extensively studied in different types of cancer especially the colon cancer but a very few studies have yet been reported regarding the discovery of inhibitors for the treatment of colon cancer by targeting these isozymes." (PMID 36301939, 2022). "In order to examine whether AKR1B1 expression from the neoplastic cells or tumor stroma is correlated specifically with stromal content, AKR1B1 expression was evaluated individually for neoplastic cells and tumor stroma via IHC in colon tumors obtained from Serbian patients." (PMID 40396420, 2025). "Moreover, fidarestat, an AKR1B1 inhibitor, decreased COX2 and NF-κB on HT29 colon cancer cells and inhibited PKC, AKT and COX2 in azoxymethane-induced colonic premalignant mice." (PMID 36552555, 2022). "Previous studies have demonstrated that AKR1B1 inhibition by sorbinil and zopolrestat hinders EGF/FGF-induced growth, migration and invasion through GS-DHN oxidative stress mediator-induced NF-κB activation on HT29 and KM20 colon cancer cells." (PMID 36552555, 2022).
colorectal cancer (14 papers, 2019 to 2025). A primary or metastatic malignant neoplasm that affects the colon or rectum. "While studying colorectal cancer using gene enrichment analysis, tumor genome atlas, and RNAseq data, AKR1B1 expression was associated with cell cycle progression, movement, and inflammation." (PMID 37751590, 2023). "AKR1B1, a member of the aldo‐keto reductase enzyme family involved in the polyol pathway of aldehyde metabolism, is aberrantly expressed in colorectal cancer (CRC)." (PMID 40396420, 2025). "High expression of AKR1B1 was observed in bladder and renal carcinomas with decreased expression in invasive breast cancer, colorectal cancer (CRC), adrenal cortex, and prostate cancer." (PMID 39055885, 2024). "In colorectal carcinoma, the AKR1B1 and AKR1B10 expression levels in tumor cells, both AKR family members, and their effect on the proliferation ability of tumor cells showed opposite trends." (PMID 37751590, 2023). "Several pieces of evidence suggest that the expression of AKR1B1 varies greatly in different stages of colorectal cancer (CRC)." (PMID 34568042, 2021). "However, AKR1B1 expression promotes tumor cell proliferation with the colorectal cancer progression." (PMID 37751590, 2023). "In addition, AKR1B1 enhances cell motility and NF-κB activity, resulting in a poor prognosis in colorectal cancer patients." (PMID 33302403, 2020). "In colorectal cancer cells, AKR1B1 affects cellular proliferation and cell cycle progression." (PMID 33302403, 2020). "There is still debate on how the expression of AKR1B1 affects cancer but some evidence suggests that expression of AKR1B1 in colorectal cancer (CRC) could be different depending on the stages, types and invasiveness of tumours, at least in mice models or cell lines." (PMID 32633024, 2020). "The decreased level of AKR1B1 was reported to be involved in small percent of colorectal cancer, whereas decreased expression of AKR1B10 was found in most of colorectal cancer samples." (PMID 35178443, 2022). "For colorectal cancer cells, AKR1B1 affects cellular proliferation and cell cycle progression, cell motility and expression of nuclear factor kappa-light-chain-enhancer of activated B cells (NFKB) resulting in a poor prognosis for colorectal cancer patients." (PMID 39529665, 2024). "The overexpression of AKR1B1 has been reported in breast, ovarian, cervical, lung, hepatocellular, and rectal cancer, but down-regulation of AKR1B1 has been observed in adenocarcinoma samples compared to adjacent nontumor tissue in endometrial and colorectal cancer." (PMID 34298614, 2021).
gastric cancer (13 papers, 2014 to 2025). A primary or metastatic malignant neoplasm involving the stomach. "High expression of AKR1B1 was also associated with worse prognosis in gastric cancer and breast cancer, and with favorable prognosis in endometrial cancer (when combined with the expression of AKR1B10)." (PMID 40396420, 2025). "Within this family, AKR1B1 has been implicated in gastric cancer progression, regulated by the binding of ZNF521 and EB1, promoting proliferation, migration, and invasion of gastric cancer cells." (PMID 38440405, 2024). "Elevated expression of AKR1B1 was associated with metastasis and lower overall survival in gastric cancer patients." (PMID 39055885, 2024). "In gastric cancer, AKR1B1 expression was significantly high and associated with TNM staging indicating its prognostic significance." (PMID 39055885, 2024). "In gastric cancer, AKR1B1 overexpression was associated with activation of the AKT-mTOR pathway." (PMID 39055885, 2024). "In gastric cancer, AKR1B1 plays a pro-tumorigenic role through modulation of ferroptosis via interaction with STAT3 and p-STAT3." (PMID 41154825, 2025). "Additional evidence from gastric cancer has shown that fructose generated via AKR1B1 activity activates a novel KHK-A/YWHAH/SLUG signaling axis that represses E-cadherin and induces EMT, a key mechanism underlying cancer cell detachment and invasiveness." (PMID 41154825, 2025). "AKR1B1 promotes the tumorigenicity and metastasis of triple-negative breast cancer and the invasiveness of cervical and gastric cancers." (PMID 40361399, 2025). "For a subcutaneous xenograft model, SNU-638, which originally arose from a diffuse type of gastric cancer, was established to stably coexpress luciferase and AKR1B1." (PMID 38200154, 2024). "Of the three CDH1 repressors SNAIL, SLUG, and TWIST, YWHAH robustly interacted with SLUG in gastric cancer cells, which was inhibited by silencing AKR1B1 and/or SORD." (PMID 38200154, 2024). "Spearman correlation analysis using the GSE2685 gastric cancer dataset revealed that AKR1B1 expression was inversely correlated with CDH1 expression." (PMID 38200154, 2024). "In two xenograft models of gastric cancer, AKR1B1 overexpression increased metastasis in diabetic mice." (PMID 38200154, 2024). "In two different xenograft models of cancer metastasis, gastric cancers overexpressing AKR1B1 were found to be highly metastatic in diabetic mice, but these effects of AKR1B1 were attenuated by KHK-A knockdown." (PMID 38200154, 2024). "A chi-square analysis revealed that gastric cancers with elevated expression of both AKR1B1 and SORD are more aggressive." (PMID 38200154, 2024). "AKR1B1 expression correlated positively with age, invasion, metastasis, staging, and prognosis of gastric cancer." (PMID 39055885, 2024). "The sedative propofol reduced the proliferation of BGC823 and GES-1 gastric cancer cells by significantly decreasing the expression of both AKR1B1 and AKR1B10 via the NRF2-mediated polyol pathway." (PMID 39055885, 2024). "We first established stable MKN-28 cell lines, which were originally derived from intestinal gastric cancer, that stably coexpressed luciferase and AKR1B1 and verified the luciferase activity and AKR1B1 expression." (PMID 38200154, 2024). "The positive AKR1B1 expression levels among normal and cancer gastric cancer tissues were 43.5% and 26.1%, respectively." (PMID 37751590, 2023). "The AKR1B1 gene in six kinds of immune cell infiltration results was extremely significant in gastric cancer." (PMID 36140749, 2022). "To examine whether the polyol pathway is involved in gastric cancer progression, we focused on AKR1B1, which is the rate-limiting enzyme in the pathway." (PMID 38200154, 2024). "In contrast to AKR1B1, AKR1B10 expression was significantly decreased in gastric cancer and associated with tumor size, stage, and metastasis, suggesting that AKR1B10 may be a reliable prognostic indicator." (PMID 39055885, 2024).
gastric cancer (continued). "AKR1B1 was identified as a core gene for the regulation of the immune microenvironment, a biomarker for prognosis, and a potential target for gastric cancer treatment based on weighted gene co-expression network analysis, and data from The Cancer Genome Atlas-stomach adenocarcinoma and GSE62254." (PMID 39055885, 2024). "AKR1B1 as a common high-expressed gene in cancer, including gastric cancer, may lead to increased proliferation, metastasis and invasion of tumor cells by driving the epithelial-tomesenchymal transition (EMT)." (PMID 34646828, 2021). "One recent study has shown that high expression of AKR1B1 in gastric cancer cells was associated with immunosuppressive immune cell infiltration and worse prognosis, although it was not reported whether the stromal cells expressed any AKR1B1." (PMID 40396420, 2025). "In this study, the gastric cancer patients with high expression of CTLA4 and ENTPD2 had a better survival prognosis, with high expression of CLDN6, EMB, GPR15, VWF and AKR1B1 suggesting poor prognosis, which was consistent with previous studies." (PMID 37066015, 2023). "After meta-analysis of GC gene expression profile chip, it was found that 7 of these genes, including AKR1B1, CTSK, MMP2, TLR4, ADRB2, PDE1C, and PTGER3, had significant differences in gastric cancer tissues." (PMID 34646828, 2021). "Two enzymes, AKR1B1 and SORD, in the polyol pathway were analyzed in human gastric cancer tissues." (PMID 38200154, 2024). "Increased mRNA expression of AKR1B1, AKR1C2, and carbonyl reductase (CR) and induction of carbonyl-reducing enzymes AKR1B1 and AKR1C2 can account for drug resistance to some anticancer agents, for instance, the resistance of human stomach carcinoma cells to daunorubicin." (PMID 24648844, 2014).
hepatocellular carcinoma (13 papers, 2002 to 2025). A malignant tumor that arises from hepatocytes. "Inhibition of AKR1B1 caused hepatoma cells to become more sensitive to 3‐deoxyglucosone and glyceraldehyde, suggesting a role for AKR1B1 in cancer resistance in hepatoma cells." (PMID 32633024, 2020). "In hepatocellular carcinoma, the most common form of primary liver cancer, AKR1B1 has been shown to bind the kinase domain of AKT1, leading to activation of the AKT/mTOR pathway." (PMID 41154825, 2025). "In hepatocellular carcinoma, AKR1B1 promotes tumorigenesis by interacting directly with key components of the AKT/mTOR signaling pathway." (PMID 41154825, 2025). "DNA chip data helped analyze the gene expression profile of drug-resistant hepatocellular carcinoma from nodules to tumor models, indicating the upregulation of the AKR1B1 expression." (PMID 37751590, 2023). "AKR1B1 downregulation is also reported in hepatocellular carcinoma, endometrial cancer, sporadic adrenocortical tumors, and prostate cancer." (PMID 37185746, 2023). "Several studies have been conducted to unveil the role of AKR1B1 in different cancers including colorectal, breast, pancreatic and hepatocellular carcinoma." (PMID 32633024, 2020). "Therefore, future studies should further clarify the exact mechanisms of EPS15 and AKR1B1 promoting hepatocellular carcinoma." (PMID 38230218, 2024). "In 1995, AKR1B1 up‐regulation was demonstrated in vivo and in vitro in hepatocellular carcinoma (HCC)." (PMID 32633024, 2020). "Therefore, EPS15-AS1 can induce ferroptosis in hepatocellular carcinoma cells by inhibiting the expression of EPS15 and AKR1B1 and disrupting the redox balance." (PMID 38230218, 2024).
diabetic nephropathy (11 papers, 2012 to 2025). "For example, variations in the aldose reductase gene, AKR1B1, impact polyol pathway activity, which has been implicated in the pathogenesis of diabetic nephropathy and retinopathy." (PMID 39857406, 2025). "We speculate that AKR1B1 enzyme activity may be associated with diabetic nephropathy." (PMID 28805547, 2017).
Insulin resistance (11 papers, 2017 to 2024). Increased resistance towards insulin, that is, diminished effectiveness of insulin in reducing blood glucose levels. "Thus, the enhanced activity of AKR1B1 promotes not only the onset of oxidative stress linked to insulin resistance but also the long-term complications linked to T2DM." (PMID 36839851, 2023). "Moreover, in a poly-pharmacology strategy, dual inhibitors of PTP1B and AKR1B1 could be used as multitarget drugs to treat both conditions of insulin resistance and chronic complications associated with T2DM." (PMID 36839851, 2023). "Both PTP1B and AKR1B1 are, thus, currently emerging as suitable targets to be modulated with drug-like small molecules to discover new therapeutics for insulin resistance and obesity." (PMID 36839851, 2023).